CRP (C-reactive protein)
Diseases named in the same sentence as CRP in open-access papers (continued):
Sharing a sentence is not in itself a finding about the gene and the disease.
Insulin resistance (continued). "Molecular markers of inflammation, such as TNF-α, IL-6, and CRP, were significantly elevated in individuals with obesity and insulin resistance, and these markers could predict the development of T2DM." (PMID 40302954, 2024). "Studies show that CRP is positively correlated with insulin resistance and body fat mass." (PMID 39768981, 2024). "CRP and TNF-α were associated with insulin resistance and ceramide production, which may be associated with reduced LV function." (PMID 38566090, 2024). "Similarly, the negative correlation between oncostatin M, homeostatic model assessment for insulin resistance, and C-reactive protein values was detected in our study." (PMID 38397957, 2024). "A smaller one-sample MR study found no causal effect of CRP on hyperglycaemia or insulin resistance, as measured by HbA1c and HOMA-IR." (PMID 38730445, 2024). "In the 24th week of the interventions, CRP levels, insulin resistance levels, and serum triglyceride levels were reduced in the patients assigned to weight loss only and those assigned to the combined interventions, while none of these changes were observed in the group treated using CPAP alone." (PMID 38892846, 2024). "Insulin resistance in type 2 diabetes patients is responsible of the production and release of several cytokines, leading to the hepatic overproduction of acute phase proteins such as C- reactive protein, serum amyloid A, and plasminogen activator inhibitor-1." (PMID 37762893, 2023). "High ferritin levels shows a positive correlation with MetS components including serum triglycerides (TG), plasma glucose, and insulin resistance markers even after adjusting for age, race, body mass index (BMI), smoking status, alcohol consumption, and C-reactive protein (CRP) level." (PMID 37396849, 2023). "Furthermore, leptin and CRP increase insulin resistance whereas adiponectin improves insulin sensitivity; primary features of GDM." (PMID 36520252, 2023). "Insulin resistance and CRP have been used together as indicators of NAFLD." (PMID 37893085, 2023). "Other studies found cross-sectional associations between CRP and hepatic insulin resistance (HOMA-IR) in GDM women, but they did not investigate the role of weight or body fat." (PMID 37891561, 2023). "However, we showed that children, especially boys, with MAFLD present higher CRP level and insulin resistance (HOMA-IR > 3.0)." (PMID 37630857, 2023). "Accordingly, we used CRP knockout (KO) rats to construct a PCOS model to explore whether CRP gene deletion affects insulin resistance, hepatic glucose homeostasis and leptin bioactivity in PCOS rats." (PMID 37660067, 2023). "Finally, secretory PPGLs lead to subclinical inflammation, as shown by increased c-reactive protein (CRP) level and tumor necrosis factor A (TNF-α), which is recognized to be associated with insulin resistance." (PMID 37731140, 2023). "On the one hand, insulin resistance could slow the healing process of the wound, and inflammatory reactions might produce inflammatory factors that influence homeostasis, such as CRP and IL-6." (PMID 37653410, 2023). "Studies have shown that HP infection induces the release of pro-inflammatory cytokines such as tumor necrosis factor alpha, interferon gamma, interleukin (IL)-1, IL-6, IL-8, IL-10, IL-12, and C reactive protein and was shown to be involved in the pathogenesis of insulin resistance." (PMID 36699110, 2023). "Research conducted with a multiethnic Asian population has shown that TV viewing was associated with increased systolic blood pressure and other health indicators such as high total cholesterol, triglycerides, and C-reactive protein levels, insulin resistance, and lower adiponectin levels." (PMID 37608246, 2023). "It has been recognized that CRP elevation is independently related to insulin resistance and may be related to coronary heart disease and cardiovascular events in PCOS." (PMID 37509682, 2023).
Insulin resistance (continued). "Additionally, the role of CRP in the development of insulin resistance by affecting the insulin signaling pathway in hepatocytes, skeletal muscle, and endothelial cells has been described." (PMID 35883605, 2022). "On the other side, high-intensity PA induced an improvement in inflammatory biomarkers and insulin resistance, with a reduction in IL-6, TNFa, CRP, and resistin and an increase in adiponectin, thus indicating that exercise exerts anti-inflammatory and insulin-sensitising effects." (PMID 35679338, 2022). "Since this study used secondary data derived from the KNHANES, we could not collect data on sex hormone prescriptions, such as estrogen or testosterone; inflammatory markers, such as CRP or IL-6; or insulin resistance markers, such as HOMA-IR." (PMID 36362539, 2022). "CRP and TNF-α are associated with insulin resistance and atherosclerosis." (PMID 35548430, 2022). "Moreover, DM-MAFLD had a higher level of homeostasis model assessment of insulin resistance and high sensitive C-reactive protein, compared to the other groups of MAFLD." (PMID 35639744, 2022). "Studies have shown that the abundance of Subdoligranulum is positively correlated with microbial richness and HDL-cholesterol levels, and negatively correlated with fat mass, adipocyte diameter, insulin resistance, leptin, insulin, CRP, and IL6 levels in people and animals." (PMID 36611702, 2022). "In agreement, our study showed independent associations between CRP and HOMA-IR with abdominal VAT mass, supporting previous studies showing that increased abdominal VAT leads to development of pro-inflammatory state and insulin resistance." (PMID 35241101, 2022). "Carotenoids also exert positive effects on inflammation by inhibiting lipoxygenase activity, C-reactive protein, and inflammatory cytokines, which could contribute to prevention of insulin resistance." (PMID 36245540, 2022). "It is associated with elevated C-reactive protein (CRP) levels, insulin resistance, hepatitis, ballooning, and fibrosis, but not fatty liver." (PMID 36438601, 2022). "We aimed to assess the association between Dual-energy X-ray Absorptiometry-derived VAT and cardiometabolic outcomes (triglycerides, cholesterol, insulin resistance, C-reactive protein, and blood pressure) in 9–12 year-old girls (73% Hispanic), controlling for body mass index (BMI) percentile." (PMID 36172390, 2022). "However, insulin sensitivity is inversely related to the RMR, which indicates that with consumption of UPFs, hs-CRP levels, inflammation, and insulin resistance increase, which has a decreasing effect on the RMR." (PMID 36313082, 2022). "The elevation of HDL-c and PON-1, an enzyme that protects LDL from lipid peroxidation, was found after egg ingestions; therefore, individuals with metabolic syndrome who had consumed eggs presented a decrease in C-reactive protein levels, insulin levels, and insulin resistance, compared to baseline." (PMID 36313094, 2022). "Historically, clinical values including HbA1c, intact proinsulin, adiponectin, and high sensitivity C-reactive protein have been suggested as biomarkers of β-cell failure and insulin resistance, although their overall useability is limited, as both specificity and context need to be considered." (PMID 36557272, 2022). "Lower plasma DMO concentrations were associated with higher glucose and TG levels and homeostasis model assessment of insulin resistance (HOMA-IR), while higher plasma OLA concentrations were associated with higher CRP and homocysteine levels in the OLA-treated patients with schizophrenia." (PMID 35800023, 2022). "Insulin resistance caused by obesity is related to the development of a chronic low-grade inflammatory state and the action of adipokines, such as leptin, resistin, TNF-α, IL-6, MCP-1, and CRP." (PMID 36262532, 2022).
Insulin resistance (continued). "Nevertheless, there is still uncertainty whether the inflammation is due to the PCOS itself or to insulin resistance and obesity, and more studied are needed to understand the precise mechanism of elevation of CRP concentrations in PCOS women." (PMID 33917519, 2021). "This combination of increases in intestinal permeability and plasma LPS levels induce the production of pro-inflammatory cytokines (ILs, TNF-α) and CRP that can in turn induce the serine phosphorylation of insulin receptor substrate-1, leading to insulin resistance." (PMID 34692563, 2021). "A recent randomized trial reported that probiotic consumption 8 × 109 vs. placebo, was related to a decrease in 4.8 points in the MDS-UPDRS score, along with a decrease in C-reactive protein, malondialdehyde and insulin levels; whereas insulin resistance improved and glutathione levels increased." (PMID 34566874, 2021). "The stepwise regression analysis revealed less leg strength, homeostasis model assessment of insulin resistance, and C-reactive protein as an independent predictor of serum adiponectin levels based on the significance of the univariate analysis (R2 = 0.190, P < 0.001)." (PMID 33465151, 2021). "IL-6 seems to induce insulin resistance and an increased production of CRP in the liver and TNF-α may also induce insulin resistance by suppressing the expression of the insulin-sensitive glucose transporter in peripheral tissues." (PMID 34650454, 2021). "In addition, it has been shown that 10 nm GNPs control hyperglycemia in diabetic rats via regulating blood glucose levels, insulin resistance, pro-inflammatory mediators (CRP, IL-6 and TNF-α), and liver enzymes." (PMID 34572503, 2021). "However, in some of the included studies that did not measure HbA1c levels, other positive changes in systemic parameters such as interleukin (IL)-6 levels, high-sensitive C-reactive protein levels, insulin, and insulin resistance were obtained." (PMID 34439554, 2021). "It has been reported in obese subjects that 24 weeks of moderate- to high-intensity physical training reduced the circulating levels of markers of subclinical inflammation such as C-reactive protein (CRP), resistin, and concomitantly improved insulin resistance." (PMID 32737757, 2021). "Possible mechanisms of pathogenesis of NAFLD induced by H. pylori include (i) insulin resistance; (ii) inflammatory cytokines or adipokines, particularly CRP, TNF‐α, and IL‐6; (iii) altered lipid profile; and (iv) altered intestinal permeability and gut microbiota." (PMID 33490615, 2021). "Similarly, folic acid supplementation significantly lowered CRP serum levels, probably owing to the improvement of insulin resistance, oxidative stress, and hyperhomocysteinemia." (PMID 33026590, 2021). "High %BF in this population was associated with higher leptin and higher CRP concentrations, which have been closely linked to insulin resistance, a known risk factor for noncommunicable diseases." (PMID 33680494, 2021). "The production of TNF-alpha, IL-6, and CRP from adipose tissue influences insulin resistance." (PMID 34403431, 2021). "It has been speculated that inflammatory markers such as tumor necrosis factor-alpha (TNF-α), interleukin (IL) 6, and C-reactive protein (CRP) impact on endothelium dysfunction and insulin resistance and contribute to the pathogenesis of GDM." (PMID 33918528, 2021). "In addition, clinical studies have shown that sleep deprivation increases levels of Interleukin 6 (IL-6) and C-reactive protein (CRP), both of which have been linked to MetS constituents through increased insulin resistance." (PMID 34670597, 2021). "Consistently, elevation of systemic inflammatory responses in relation to sleep restriction was also well demonstrated, and proinflammatory cytokines such as tumor necrosis factor and C-reactive protein were released and subsequently promoted insulin resistance." (PMID 34556157, 2021). "smoking and CRP, are strongly correlated with insulin resistance." (PMID 34104095, 2021).
Insulin resistance (continued). "Elevated levels of TNF-α and IL-6 could also trigger the synthesis of C-reactive protein (CRP) in the liver, which is a common systemic inflammatory biomarker and invariably correlates with insulin resistance and the pathogenesis of T2DM." (PMID 34955840, 2021). "Similarly, positive associations were observed for markers of insulin resistance (HOMA-IR, fasting insulin, reduced insulin sensitivity, increased leptin and reduced adiponectin) and systemic inflammation (c-reactive protein)." (PMID 32958048, 2020). "Among them, one interesting significant association was for weight, waist, CRP, and WBC involved in Relaxin signaling pathway, which has been reported to have a function in the treatment of diet-induced insulin resistance and vascular dysfunction in mice model." (PMID 32900998, 2020). "Furthermore, we observed that insulin, insulin resistance, and C-reactive protein (CRP) were lower during egg intake compared to baseline, an effect not seen with the choline supplement." (PMID 33066009, 2020). "The infiltration of inflammatory cells into adipose tissues leads to the increased secretion of proinflammatory cytokines and chemokines such as TNFα, MCP-1, C reactive protein (CRP), and interleukins, and these same inflammatory mediators have been shown to be upregulated in insulin resistance." (PMID 32971975, 2020). "Additionally, in hypertensive patients with cerebral infarction, inflammation (hs-CRP and IL-6 levels) and insulin resistance by homeostatic model assessment insulin resistance (HOMA-IR) index were associated with the diameter of the cerebral infarct." (PMID 33375333, 2020). "A critical observation from the analysis is that the concentration of inflammatory markers in female adolescents was associated with the Inactive & Sedentary latent class, body fat percentage (BF%), high-sensitivity C-reactive protein (hs-CRP), and insulin resistance." (PMID 32694929, 2020). "The increase of CRP may lead to apoptosis of β-cells by activating NF-κB and participate in insulin resistance (IR) and the pathogenesis of T2DM." (PMID 33456672, 2020). "High ferritin levels without significant iron overload may affect glucose homeostasis, leading to insulin resistance and inflammatory changes, such as elevated CRP levels." (PMID 32280714, 2020). "This may explain why the impact of increasing BMI on insulin resistance, C-reactive protein, and adiponectin levels is more pronounced in Chinese than in the other ethnic groups in Singapore76." (PMID 32523012, 2020). "Systolic and diastolic blood pressure were higher in the UK cohort (p < 0.001), whilst testosterone (p < 0.02), glucose (p < 0.001), WCC (p < 0.001), HDL (P < 0.001), CRP (p < 0.001), insulin and insulin resistance (p < 0.001) were higher in the Middle Eastern cohort without PCOS." (PMID 33144665, 2020). "In addition, a large retrospective study demonstrated a positive correlation between insulin resistance and C-reactive protein levels." (PMID 32622367, 2020). "Higher percentage methylation of the two FKBP5 CpG sites correlated with adiposity (body mass index and waist circumference), insulin resistance (homeostasis model for insulin resistance, fasting insulin and plasma adipokines) and systemic inflammation (c-reactive protein) in both adipose depots." (PMID 32958048, 2020).
Insulin resistance (continued). "Thus, our study confirms that systemic inflammation due to high hs-CRP levels has an independent effect on insulin resistance, as estimated by the TyG index." (PMID 33116232, 2020). "Furthermore, GlycB has weaker relationships with CRP and measures of insulin resistance and adiposity than GlycA." (PMID 32012794, 2020). "This relationship may be mediated by the increase in some inflammatory markers such as insulin resistance or C-reactive protein." (PMID 30934975, 2019). "CRP (OR: 3.29; 95% CI: 1.13–9.56; p<0.02) was the most important predictor of insulin resistance." (PMID 30735527, 2019). "In addition, the metabolic syndrome group had significantly higher high-sensitivity C-reactive protein (hs-CRP) and Homeostatic Model Assessment Insulin Resistance (HOMA-IR) levels than the control group." (PMID 30862094, 2019). "This study demonstrates that elevated CRP is associated with future insulin resistance in non-diabetic adults, and their joint effect is predictive of the development of T2DM." (PMID 31443647, 2019). "Is important to take into account that empagliflozin may decrease hs-CRP and reduce the levels of lipoproteins via ameliorating insulin resistance." (PMID 31683785, 2019). "In noncancer populations, CRP and insulin resistance have been associated with neurocognitive impairment." (PMID 31605514, 2019). "Statins can reduce levels of CRP and IL-6, and improve insulin resistance." (PMID 31439071, 2019). "Insulin resistance correlated with the reduction in CRP as well-described by others." (PMID 31001199, 2019). "Endothelial dysfunction is one of the earliest steps in the atherosclerotic process and was reported to be correlated with several cardiovascular risk factors, including dyslipidemia, smoking status, obesity, insulin resistance, diabetes, hypertension, and CRP." (PMID 30274193, 2018). "Also, its relation with metabolic parameters like higher CRP concentrations or markers of glucose intolerance and insulin resistance has been confirmed in several previous studies." (PMID 29439738, 2018). "In non-asthmatic patients, WHtR is linked to the homeostasis model assessment of insulin resistance (HOMA-IR) and is associated with increased lipolysis and atherogenic dyslipidaemia: this result promotes inflammation and the hepatic synthesis of C-reactive protein (CRP)." (PMID 30400197, 2018). "This study aimed to investigate the potential early prediction role of urinary vitamin D-binding protein (uVDBP) for the diagnosis of DN and to examine the possible correlation to serum VDBP, high-sensitivity C-reactive protein (hs-CRP), and insulin resistance in these patients." (PMID 29850609, 2018). "A suspected mechanism that increased central adiposity and insulin resistance due to chronic low-grade inflammation of MetS might increase the production of CRP in the liver." (PMID 29382113, 2018). "Moreover, all participants with signs of insulin resistance and a high CRP were in the N-BMI-HF group." (PMID 29914129, 2018). "In multiple regression models, Faecalibacterium was significantly associated with fasting glucose; Collinsella (directly) and Blautia (inversely) with insulin, and with Homeostasis-Model Assessment Insulin-Resistance, while Sutterella with C-reactive protein levels." (PMID 30111822, 2018). "A recent study found that WBS application to the abdomen for 12 weeks was effective in reducing a proinflammatory state (as observed by TNF-α, adiponectin, and C-reactive protein levels), as well as fasting glycemia, insulin resistance, and visceral adiposity in obese diabetics." (PMID 30382930, 2018). "Systemic inflammation level was assessed by serum high-sensitivity C-reactive protein (hs-CRP), and the degree of insulin resistance and beta-cell function were evaluated by the homeostasis model assessment insulin resistance (HOMA-IR) and beta-cell function (HOMA-β), respectively." (PMID 28575103, 2017).